PRL (prolactin)
Diseases named in the same sentence as PRL in open-access papers (continued):
Sharing a sentence is not in itself a finding about the gene and the disease.
pituitary adenomas (continued). "For example, in prolactinomas of pituitary adenomas, dopamine-D2 receptor agonist therapy is an effective method to control prolactin levels and preserve gonadal function, as dopamine has the capacity to inhibit prolactin secretion." (PMID 40708904, 2025). "The degree of increase in prolactin concentration in the metoclopramide test, as well as the result of the daily prolactin profile allowed the exclusion of a pituitary adenoma of the prolactinoma type." (PMID 40917349, 2025). "Diagnosis of prolactinoma requires the presence of a sellar lesion consistent with a pituitary adenoma in conjunction with elevated serum prolactin (typically >250 μg/L with elevation in prolactin in proportion to adenoma size)." (PMID 40004619, 2025). "These neurological symptoms, coupled with the mildly elevated serum prolactin level of 609.10 μIU/mL, raised concerns for potential intracranial pathology, particularly pituitary involvement, such as a pituitary adenoma." (PMID 40656428, 2025). "Factors associated with a lower rate of surgical cure (immediate surgical cure) in GH&PRL co-secreting pituitary adenomas." (PMID 40590355, 2025). "Regarding the response to fgSRL in monotherapy, 18% of the patients with GH&PRL pituitary adenomas were classified as resistant." (PMID 40590355, 2025). "The clinical presentation, tumor growth behavior and response to treatment of GH and PRL co-secreting pituitary adenomas (GH&PRL-PAs) can be heterogeneous." (PMID 40590355, 2025). "For example, in patients with pituitary adenoma (N = 4) receiving cabergoline, prolactin function cannot be interpreted." (PMID 40851073, 2025). "Prolactin (PRL)-secreting tumors constitute approximately 53% of pituitary adenomas and are the most prevalent type in children." (PMID 40708904, 2025). "Prolactin-secreting pituitary adenomas (prolactinomas), classified as pituitary neuroendocrine tumors (PitNETs), represent approximately 53% of all pituitary adenomas and originate from lactotroph cells." (PMID 41293742, 2025). "Prolactinomas are prolactin (PRL)-secreting pituitary adenomas derived from lactotroph cells and constitute the majority of hormone-secreting intra-sellar tumors in both women and men." (PMID 39900728, 2025). "Histopathological and immunohistochemical analyses confirmed somatotroph pituitary adenomas in all cases, with co-expression of prolactin in eight patients." (PMID 41573472, 2025). "At the time of cabergoline discontinuation, both groups had similar prolactin levels [median 6.0 (2.5–10.0) ng/ml vs 4.0 (1.0–7.0) ng/ml], testosterone levels (5.8 ± 1.7 ng/ml vs 5.2 ± 2.4 ng/ml), and mean pituitary adenoma size (3.0 ± 1.4 mm vs 3.8 ± 1.3 mm)." (PMID 40199840, 2025). "Despite TSH-producing pituitary adenoma presenting similar findings in regard to thyroid hormones as in our patient, the elevated level of prolactin indicates the pituitary as a whole was likely being stimulated." (PMID 40236334, 2025). "Prolactinoma is a common pituitary adenoma that occurs in individuals with hypothalamic-pituitary disease and is characterized by excessive secretion of prolactin (PRL) from anterior pituitary lactotroph cells." (PMID 38572480, 2024). "Prolactinoma are characterized by the excessive secretion of prolactin and account for approximately 30–45% of all pituitary adenomas, they represent the most common type of functional pituitary adenomas." (PMID 39085706, 2024). "Most of the pituitary adenomas have a young age of onset and secrete growth hormone (GH) only or both GH and prolactin." (PMID 38479600, 2024). "Most cases of pituitary adenomas are described as functional (usually secreting either prolactin or growth hormone)." (PMID 39221401, 2024). "The prevalence and incidence of prolactin-secreting pituitary adenomas (PSPAs) is approximately 50 per 100,000 and 3–5 new cases per 100,000 per year, respectively." (PMID 38375408, 2024).
pituitary adenomas (continued). "In autopsy studies, the prevalence is much higher, as pituitary adenomas have been identified in up to 11% of the autopsies, with almost half showing positive immunohistochemistry for prolactin." (PMID 38578472, 2024). "Diagnosis and treatment history: In the given case, the model correctly recognizes the primary diagnosis (prolactin-producing pituitary adenoma) and the past treatment of transsphenoidal surgery in the clinic of the recipient." (PMID 39877751, 2024). "Patients with very high levels of prolactin resulting from pituitary adenomas have increased migraine attacks that have been shown to respond to treatment by dopaminergic agonists that reduce prolactin levels." (PMID 38658853, 2024). "The main treatment option of prolactin-secreting pituitary adenomas is dopamine agonist therapy, which demonstrates prolactin level normalizing and reducing the size of an adenoma in the majority of cases." (PMID 38311996, 2024). "In most cases, it is caused by pregnancy, hypothalamic-pituitary disconnection or PRL-secreting pituitary adenomas (prolactinomas), or it can also be secondary to the use of medications." (PMID 38765533, 2024). "In most cases, it is caused by pregnancy, hypothalamic-pituitary disconnection, or prolactin-secreting pituitary adenomas (prolactinomas), but it can also be secondary to the use of medications." (PMID 38578472, 2024). "In most cases, HPRL is caused by pregnancy, hypothalamic-pituitary disconnection or PRL-secreting pituitary adenomas (prolactinomas), or it can also be secondary to drug use." (PMID 38765533, 2024). "Among them, 31.8% had a known pituitary adenoma, and it was in all cases a macroadenoma, predominantly a prolactin secreting tumor (42.8%)." (PMID 37391784, 2023). "Immunostaining of tumor tissue collected intraoperatively showed GH- and prolactin-producing cells, leading to the diagnosis of an GH- and prolactin-producing pituitary adenoma." (PMID 36508085, 2023). "In 50 human pituitary adenomas, including 25 NFPA and 25 secreting adenomas (10 GH, 5 PRL, 6 LH and/or FSH, 4 GH/PRL), only one V600E mutation in a NFPA sample was found, suggesting that B-RAF mutations are a rare event in pituitary tumorigenesis." (PMID 37446128, 2023). "Of the ectopic sites in which pituitary adenoma occurs, clival adenomas are rare and the majority secrete prolactin." (PMID 37908213, 2023). "The patient underwent transsphenoidal surgery and histopathology showed a pituitary adenoma with frequent immunoreactive cells for GH and rarer for prolactin and with areas of recent and old intratumoral haemorrhage, suggestive of pituitary apoplexy." (PMID 37149543, 2023). "A retrospective study, that diagnosed 528 women with PCOS by medical records, showed elevated prolactin levels in 11.4% of which 43.2% of these women had pituitary adenomas." (PMID 37854182, 2023). "PRL levels greater than 200 ng/mL indicate a PRL-producing PitNET/pituitary adenoma, often a macroadenoma (macroprolactinoma) larger than 1 cm in size." (PMID 36826759, 2023). "The most common cosecreting pituitary adenomas are TSHomas (37.9%), and their most common cosecreted hormone is GH (57.5%), followed by prolactin (41.4%), FSH (26.5%), and LH (8.8%)." (PMID 37988667, 2023). "In prolactin-producing pituitary adenomas (PRL-PAs), research has identified widespread genomic copy number amplifications, which correlate with transcriptomic changes in this tumor subtype." (PMID 38275385, 2023). "Preoperative management of growth hormone and prolactin levels facilitates an increased remission rate of these hormones post pituitary adenoma surgery." (PMID 37964947, 2023). "The combined application of somatostatin analog, DA, or D2 receptor agonist effectively reduce the secretion of a large amount of PRL by pituitary adenoma cells through physiological feedback mechanisms and inhibit the growth of tumors." (PMID 37649087, 2023).
pituitary adenomas (continued). "Treatment of dopamine agonists (DAs) effectively normalized their prolactin level and the pituitary MRI reexamination after 6 months of DAs treatment showed the shrinkage of the pituitary adenomas in 3 patients." (PMID 38093965, 2023). "Clinical trial results have shown that the D2 receptor was highly expressed on the surface of pituitary adenoma cells and its stem cells in patients with pituitary adenoma with a significant secretion of PRL." (PMID 37649087, 2023). "Even though all individuals in family 2 who participated in the study had PHPT, they also had other endocrine tumors that are part of the clinical condition of MEN1, such as pituitary adenomas secreting prolactin and GH, insulinoma, and adrenal tumors." (PMID 36967793, 2023). "Prolactinomas or lactotrophic adenomas are the most common pituitary adenomas, accounting for approximately 50% of all pituitary adenomas and are characterized by excessive prolactin secretion (levels > 150–200 ng/mL)." (PMID 37249700, 2023). "About half of pituitary adenomas are known to secrete specific hormones, most frequently prolactin, growth hormone, or adrenocorticotropic hormone." (PMID 38275385, 2023). "Concerning prolactinomas, the most common functional pituitary adenomas, the treatment with dopamine agonists usually leads to normalization of the serum prolactin level and shrinking of the tumor mass." (PMID 37446128, 2023). "miR-375 is highly expressed in prolactin-secreting pituitary adenomas (prolactinomas) and has been shown to regulate prolactin secretion by targeting the prolactin gene." (PMID 37446128, 2023). "In a study of young patients with pituitary adenomas, the highest BMI at diagnosis was measured in prolactinoma patients, with ongoing weight gain in some patients despite normalization of PRL levels." (PMID 36814862, 2023). "We also examined HDAC1, HDAC2, and HDAC3 expression by qRT-PCR in six GH-secreting, six ACTH-secreting, and six PRL-secreting human pituitary adenomas." (PMID 35646715, 2022). "In these patients, measurement of prolactin (PRL) levels is justified to reveal or exclude the presence of a PRL-secreting pituitary adenoma." (PMID 35349114, 2022). "Pathological diagnosis of pituitary adenoma was made with immunohistochemistry reports of positive GH, luteinizing hormone (LH), and scattered positive prolactin (PRL)." (PMID 36619586, 2022). "Tau amyloid is associated with ganglioglioma, IAPP with neuroendocrine tumors, the N-terminus of prolactin with pituitary adenoma and ODAM with odontogenic tumors." (PMID 36232958, 2022). "While 39 (71%) patients had a prolactin-producing pituitary adenoma (group A), 16 (29%) patients had a sellar lesion other than prolactinoma (group B)." (PMID 36147567, 2022). "A similar mechanism was also observed in prolactin pituitary adenomas where FOXO1 suppresses the promoter of PRL gene." (PMID 35270010, 2022). "Thyrotropin-secreting pituitary neuroendocrine tumors (PitNETs) are rare pituitary adenomas that are occasionally accompanied by hypersecretion of other anterior pituitary hormones, such as growth hormone (GH) and prolactin (PRL)." (PMID 36539773, 2022). "As far as we know, 55% of pituitary adenomas have been reported to secrete approximately two to three hormones at the same time, among which 42% produce GH and prolactin, 7% produce GH and TSH, and 6% produce GH, TSH, and prolactin." (PMID 36619586, 2022). "In patients with small sellar lesions, Prolactin-Volume-Ratios >100 represents a possible predictive marker for the diagnosis of prolactin-producing pituitary adenomas." (PMID 36147567, 2022).
pituitary adenomas (continued). "Our study population consisted of 39 patients (71%) with a prolactin-producing pituitary adenoma (group A), while 16 patients (29%) had another type of sellar lesion (group B)." (PMID 36147567, 2022). "Recently, the use of the Prolactin-Volume-Ratio (PVR), has been proposed as a helpful diagnostic tool within the entity of pituitary adenomas to distinguish prolactinomas from other adenomas, independent of tumor size and volume." (PMID 36147567, 2022). "Within the morphogenetic expression programs, the pituitary hormone expression pathways were analyzed in order to correlate them with the prolactin-secreting histologic differentiation of the M6 pituitary adenoma." (PMID 35978432, 2022). "Growth hormone (GH)- and, less frequently, prolactin (PRL)-secreting pituitary adenomas have been reported." (PMID 35743266, 2022). "The prevalence of prolactin-secreting pituitary adenoma (PRLoma) in our whole cohort was found to be 2.8%, slightly higher than the one reported in the literature (0.3 - 0.5%)." (PMID 35250884, 2022). "Prolactinoma, a prolactin (PRL) secreting functioning pituitary tumor, is the most common of all pituitary adenomas (PA) accounting for 40-60% and dopamine agonists (DA) are the cornerstone of treatment." (PMID 36337795, 2022). "Plurihormonal pituitary adenoma (PPA) is a type of pituitary adenoma that expresses two or more types of pituitary adenoma hormones in addition to growth hormone/prolactin or follicle-stimulating hormone β subunit/luteinizing hormone β-subunit." (PMID 35284477, 2022). "Prolactinoma, a prolactin-secreting functioning pituitary tumor, is the most common of all pituitary adenomas (PA) accounting for 40-60% and up to 80% if microadenomas (size less than 1 cm) are included." (PMID 36337795, 2022). "One can easily assume that information delivered to the patient, therapeutic outcome and follow-up strategy will substantially differ if a prolactin-secreting pituitary adenoma is diagnosed in addition to PCOS." (PMID 35250884, 2022). "A 19-year-old boy, after a head trauma, performed MR with the incidental finding of a pituitary adenoma (13 × 15x10mm, PRL 850 μg/L)." (PMID 34173929, 2021). "The majority of plurihormonal pituitary adenomas produce GH, PRL, and TSH because somatotroph, lactotroph, and thyrotroph cells all arise from the same progenitor." (PMID 34321093, 2021). "Prolactin (PRL)-secreting pituitary adenomas are the most common subtype of pituitary tumors able to secrete hormones." (PMID 34322092, 2021). "The pathology included 187 (74.8%) non-functioning adenomas, 40 (16.0%) GH-secreting pituitary adenomas, 3 (1.2%) PRL-secreting pituitary adenomas, and 20 (8.0%) ACTH-secreting pituitary adenomas." (PMID 34889229, 2021). "The clinical history revealed that the signs and symptoms appeared after chronic exposure to retinoic acid, anabolic androgenic steroids, and a prolactin-secreting pituitary adenoma, respectively." (PMID 33470346, 2021). "Herein, we present one patient with a prolactin-secreting pituitary adenoma (PA) refractory to comprehensive treatments, including multiple surgical resections, radiotherapy, and medical therapy, that evolved into a fatal carcinoma with intraspinal metastasis." (PMID 34715828, 2021). "Microscopic examination of pituitary tissue revealed enlarged nuclei of PRL-ir cells in pituitary adenomas compared to pituitary glands from healthy intact animals." (PMID 33823126, 2021). "Herein, we describe an unusual case of plurihormonal pituitary adenoma with triple-positive staining for adrenocorticotropic hormone, growth hormone, and prolactin." (PMID 34321093, 2021). "We retrospectively evaluated the dynamic MRI findings in 244 patients with pathologically confirmed pituitary adenomas and a diagnosis of clinically active prolactin (PRL)-producing adenomas." (PMID 33881731, 2021).
pituitary adenomas (continued). "PRL-producing adenomas were classified through imaging of the pituitary adenoma and by the presence of serum PRL concentrations exceeding 200 ng/mL." (PMID 33881731, 2021). "We describe one case of a prolactin-secreting pituitary adenoma (PA) refractory to conventional therapy that evolved into a PC with intraspinal metastasis." (PMID 34715828, 2021). "The most common hormone combinations secreted by plurihormonal pituitary adenomas are growth hormone, prolactin, and one or more glycoprotein hormones." (PMID 34321093, 2021). "In particular, in our series, APAs were identified in 0.5% of health controls, 6% of cases of primary empty sella, 12% of NFPAs, 10% of GH-secreting pituitary adenomas and 8% of prolactin-secreting pituitary adenomas." (PMID 33484410, 2021). "Cellular localization of Syt IV in the adenohypophysis of pituitary adenomas and pituitary glands of intact animals was investigated using double immunofluorescence labeling of Syt IV and PRL." (PMID 33823126, 2021). "Among the remaining 244 cases of pituitary adenomas, 55, 16, 6, and 4 produced GH, PRL, ACTH, and TSH, respectively, while the remaining 163 were clinically diagnosed as NF adenomas." (PMID 33881731, 2021). "Among the 244 pituitary adenomas, 55, 16, 6, and 4 produced growth hormone (GH), PRL, adrenocorticotropic hormone, and thyroid-stimulating hormone, respectively, while 163 were non-functioning (NF) adenomas." (PMID 33881731, 2021). "Among the 325 cases of pituitary adenomas, 297 adenomas were pathologically diagnosed at surgery, while 28 PRL-producing pituitary adenomas were diagnosed based on imaging studies and blood hormone levels." (PMID 33881731, 2021). "The second was associated with the use of anabolic androgenic steroids, and the third was related to a prolactin- secreting pituitary adenoma." (PMID 33470346, 2021). "A pathological evaluation showed pituitary adenoma with extensive expression of growth hormone and adrenocorticotropic hormone, as well as a rare expression of follicle-stimulating hormone and prolactin." (PMID 32079542, 2020). "In this study, we transfected miR-130a-3p mimic into the pituitary adenoma cells (GH3 cells) to investigate the function of miR-130a-3p in regulating PRL." (PMID 32194503, 2020). "A positive expression of ERα and ERβ has been shown in multiple subtypes of pituitary adenoma, including growth hormone, prolactin, follicle-stimulating hormone/luteinizing hormone, and ACTH-secreting adenomas and null cell adenomas." (PMID 32547488, 2020). "A prolactinoma is the most common pituitary adenoma, which is characterized by lactotroph cells secreting prolactin (PRL) and monoclonal expansion of single cells in the pituitary." (PMID 32849307, 2020). "In adults, estrogens are able to induce formation of pituitary adenomas in sensitive rat or mice strains, most of which are functional, prolactin (PRL)- and/or growth-hormone (GH)-secreting tumors." (PMID 32188093, 2020). "The combination of dual PI3K/mTOR inhibition and temozolomide has been demonstrated to synergistically inhibit tumor growth and reduce GH/PRL levels in pituitary adenoma cell lines and in a mouse GH3 tumor model." (PMID 32012988, 2020). "Prolactin immunostaining of pituitary adenomas was positive in 10/15 (66.7%) in patients with Acropara and 207/272 (76.1%) in the isolated acromegaly group (P = 0.407)." (PMID 32311048, 2020). "In sensitive rat or mice strains of both sexes, estrogen treatments promote lactotropic cell proliferation and induce the formation of pituitary adenomas (dominantly prolactin or growth-hormone-secreting ones)." (PMID 32188093, 2020). "AIP gene germline mutations have been found in young patients with familial or apparently sporadic aggressive pituitary adenomas, mostly secreting GH and/or PRL, and less responsive to conventional medical treatments." (PMID 33281746, 2020).